RN7SL336P (RNA, 7SL, cytoplasmic 336, pseudogene)
Gene: Miscellaneous RNA gene on chromosome 6 (89,090,946 to 89,091,242, forward strand). Ensembl gene ENSG00000264017.
Homologues: Orthologues: chimpanzee Metazoa_SRP (98% identical), macaque Metazoa_SRP (92% identical). Paralogues in human: RN7SL1 (87% identical), RN7SL2 (86% identical), RN7SL3 (86% identical), RN7SL126P (84% identical), RN7SL45P (84% identical), RN7SL679P (83% identical), RN7SL296P (83% identical), RN7SL220P (82% identical), RN7SL480P (82% identical), RN7SL712P (82% identical), RN7SL769P (82% identical), RN7SL322P (82% identical), and 702 more.